LOXL1 (lysyl oxidase like 1)
Diseases named in the same sentence as LOXL1 in open-access papers (continued):
Sharing a sentence is not in itself a finding about the gene and the disease.
exfoliation syndrome (continued). "Recently, two non-synonymous polymorphisms (rs1048661 G>T and rs3825942 G>A) of lysyl oxidase-like protein 1 (LOXL1), a monoamine oxidase that catalyzes the polymerization of tropoelastin to elastin, were found to be associated with increased risk for XFS and exfoliation glaucoma (XFG)." (PMID 18483563, 2008). "Interestingly, the predicted BMP-1 cleavage site at position 134 is located near the exfoliation syndrome (XFS)-associated coding variants at positions 141 (R141L) and 153 (G153D), suggesting that changes in LOXL1 processing may play a role in the pathogenesis of XFS (Aung, Chan & Khor, 2018)." (PMID 40786111, 2025). "Recently, single nucleotide polymorphisms (SNPs) in the LOXL1 gene (OMIM 153456) at 15q24.1 have been implicated in exfoliation syndrome and exfoliation glaucoma (XFG)." (PMID 18618003, 2008). "Single nucleotide polymorphisms (SNPs) in the LOXL1 gene have been implicated in exfoliation syndrome (XFS) and exfoliation glaucoma (XFG)." (PMID 18618003, 2008). "The relationship between two entities might be unqualified or not specified at the semantic level (e.g. “The LOXL1 gene is associated with exfoliation glaucoma”), or, on the other hand, semantically specified (e.g. “The LOXL1 gene is overexpressed in exfoliation glaucoma”)." (PMID 25886734, 2015). "Single nucleotide polymorphisms (SNPs) within the lysyl oxidase like-1 gene (LOXL1; rs1048661 and rs3825942) were found to confer risk to pseudoexfoliation glaucoma (XFG) through the pseudoexfoliation syndrome (XFS) in Nordic, Caucasian, and two Asiatic populations (Indian and Japanese)." (PMID 19503743, 2009). "Results of logistic regression for the outcome of pseudoexfoliation syndrome for each CLU tagging SNP, age, gender, and LOXL1 diplotype." (PMID 18806885, 2008). "However, recently the LOXL1 gene has been shown to be associated with exfoliation glaucoma (XFG), a secondary glaucoma to exfoliation syndrome (XFS)." (PMID 18432317, 2008). "However, mutations in MYOC are not found in most of patients with POAG and many individuals with polymorphisms in LOXL1 do not develop exfoliation syndrome or XFG." (PMID 20808730, 2010). "Therefore, if this association between the LOXL1 H5 haplotype is proven to be true, LOXL1 may be involved in the genetic architecture of POAG in a small fraction of southern Chinese, implying that a subgroup of POAG may share a common etiological pathway to exfoliation glaucoma." (PMID 19098994, 2008).
glaucoma (55 papers, 2008 to 2025). Increased pressure in the eyeball due to obstruction of the outflow of aqueous humor. "Its most significant ocular manifestation is an aggressive form of glaucoma associated with variants in the gene encoding lysyl oxidase-like 1 (LOXL1)." (PMID 37905384, 2023). "Genomic-wide association studies have identified LOXL1 gene as the major genetic risk factor for the development of pseudoexfoliation (PEX) glaucoma." (PMID 35328709, 2022). "The literature suggests conflicting reports related to LOXL1 gene variants and glaucoma, in particular, related to pseudoexfoliation and primary open angle glaucoma." (PMID 35563478, 2022). "Further, LOX, LOXLs and TGM2 do have their place in glaucoma; single-nucleotide polymorphism in LOXL1 has been implicated in exfoliation glaucoma." (PMID 32973273, 2020). "We recently shown that the “G” allele frequencies of both rs1048661 and rs3825942 SNPs of LOXL1 differed between pseudoexofoliation glaucoma (PEG) patients and control subjects from Saudi Arabia (p=0.0056 and p<0.0001, respectively)." (PMID 22065931, 2011). "The association of LOXL1 SNPs with other types of glaucoma, including POAG, NTG, pigmentary glaucoma, and PACG, were reviewed in this meta-analysis." (PMID 20142848, 2010). "List of coding variants identified from LOXL1 exon sequencing in South African black individuals with primary open-angle glaucoma." (PMID 20431720, 2010). "A mutational screening of LOXL1 in the southern Chinese pedigree in which we had mapped the novel glaucoma locus on 15q22–24 should help to evaluate its contributions to the development of glaucoma." (PMID 19098994, 2008). "In general, Japanese patients with XFG associated with a LOXL1 SNP show late-onset of glaucoma after 65 years of age." (PMID 18648524, 2008). "Worldwide distribution of allele frequencies and their odds ratios for the three LOXL1 SNPs across all glaucoma phenotypes including the present cohort." (PMID 18618003, 2008). "This study demonstrates that DNA sequence variants in LOXL1 are strongly associated with pseudoexfoliation and pseudoexfoliation glaucoma in a heterogeneous clinic-based population with broad ethnic diversity." (PMID 18254956, 2008). "In summary, we aimed to determine if the LOXL1 SNPs associated with XFS/XFG were involved in another secondary glaucoma." (PMID 18618003, 2008). "Also related to “ECM organization”, were 3 other genes (Fbln1, Fn1, and Loxl1) known to be associated with different types of glaucoma." (PMID 38272861, 2024). "However, three articles included in Wang’s meta-analysis, did not achieve HWE in the control group, while two articles examined the relationship between LOXL1 gene polymorphisms and primary open-angle glaucoma." (PMID 33909695, 2021). "The incidence of XFS and glaucoma is associated with LOXL1 risk and/or protective genomic variants." (PMID 34440405, 2021). "These elastotic alterations of laminar beams resulting from LOXL1 deficiency may have adverse effects on biomechanical properties of this critical structure and may predispose to glaucoma development in eyes with PEX syndrome." (PMID 21572731, 2011). "However, none of these studies identified a significant association between the LOXL1 SNPs and these subtypes of glaucoma." (PMID 20142848, 2010). "Therefore, to ascertain effects due to ethnic differences, meta-analysis of the genetic association of LOXL1 SNPs with glaucoma could be performed based on subgrouping by ethnicity." (PMID 20142848, 2010). "We demonstrated that incorporating 8 SNPs from the largest XFS GWAS, including LOXL1 variants, resulted in modest improvements in risk prediction of XFGS/XFG compared to a base model containing age, sex, IOP, and glaucoma family history." (PMID 41002966, 2025).
glaucoma (continued). "Although the total axon numbers of Loxl1−/− and wt mice were similar at 12 months of age, the axon density was borderline reduced in Loxl1−/− mice, likely due to their enlarged optic nerves, all of which indicate a mild glaucoma phenotype." (PMID 41009782, 2025). "Our longitudinal findings of age-related reductions in RGC function in Loxl1−/− mice recapitulates the human glaucoma phenotype." (PMID 41009782, 2025). "It is conceivable that Loxl1−/− mice will present worsening glaucoma phenotypes if their IOP is experimentally elevated, which is a subject for future investigation." (PMID 41009782, 2025). "Although the specific pathways have not yet been fully elucidated, molecular interventions targeting ocular collagen remodeling including LOXL1 are still expected to become one of potential targets for the treatment of glaucoma in the future." (PMID 41561623, 2025). "Cross-referencing with human genome-wide association studies data revealed overlap with glaucoma-associated genes (LTBP2, LOXL1, COL11A1, VCAM1), alongside reduced expression of Angpt and Lmx1b, linked to ocular hypertension." (PMID 41443436, 2025). "We previously reported that 129S1/SvImJ Loxl1−/− mice had enlarged optic nerves at 12 months old, an early sign of glaucoma in rodents." (PMID 41009782, 2025). "Lysyl oxidase-like 1 (LOXL1), an isoform associated with pelvic organ prolapse and pseudoexfoliation (PEX) glaucoma, has also been reported to be proteolytically processed by these proteases." (PMID 35328709, 2022). "The association between lysyl oxidase-like 1 (LOXL1) gene and PEX syndrome or glaucoma has been widely investigated." (PMID 35418653, 2022). "Other studies propose that LOXL1 gene variants associated with the disease cause decreased gene expression and therefore suggest a protective effect against XFS and glaucoma in an oxidative stress environment." (PMID 34440405, 2021). "Several of the differentially expressed genes have previously been reported to be associated with elevated IOP and/or glaucoma, including MYOC, ADAMTS10, LTBP2, LOXL1, TGFBR3, CYP1B1, and EFEMP15,28,43–45." (PMID 34385434, 2021). "Up to date, most researches about long noncoding RNA LOXL1 have focused on exfoliation syndrome or glaucoma." (PMID 33381389, 2020). "Most previous researches about long noncoding RNA LOXL1 have always focused on exfoliation syndrome or glaucoma." (PMID 33381389, 2020). "Two candidate genes associated more broadly with other subtypes of glaucoma, myocilin (MYOC), and lysyl oxidase homolog 1 (LOXL1) have shown limited association with PDS/PG." (PMID 29780638, 2018). "To capture potentially functional regulatory variants in the LOXL1 gene locus, we first performed a genome wide association study using DNA samples from a German cohort of patients with PEX syndrome/glaucoma (n=771) and healthy subjects (n=1,350)." (PMID 28534485, 2017). "Apart from XFS/XFG and POAG, there was also one study reporting the LOXL1 SNPs in primary angle closure glaucoma (PACG), two in normal tension glaucoma (NTG), and two in pigment dispersion syndrome and pigmentary glaucoma." (PMID 20142848, 2010). "We also studied the effect of four glaucoma drug medications on LOXL1 expression in primary human lens epithelial cell cultures to see if they affect LOXL1 expression." (PMID 21139690, 2010). "The LOXL1 SNPs are located in the 15q24.1 band and within a genetic locus (GLC1N) that is associated with primary open-angle glaucoma (POAG)." (PMID 18385788, 2008). "Three LOXL1 SNPs were genotyped in a patient sample (206 pseudoexfoliation, 331 primary open angle glaucoma, and 88 controls) from the Glaucoma Consultation Service at the Massachusetts Eye and Ear Infirmary." (PMID 18254956, 2008). "It is also interesting that LOXL1 polymorphisms are highly associated with both XFS and XFG, but no such association was reported for subjects only affected with primary open-angle glaucoma." (PMID 18385788, 2008).
glaucoma (continued). "Further characterization of tissues expected to be involved in glaucoma in the LOXL1 knock-out is currently underway." (PMID 18254956, 2008). "In contrast, the same study also demonstrated decreased LOXL1 expression in PEX glaucoma specimens." (PMID 35348588, 2022). "Moreover, LOXL1, the major susceptibility gene for PEX syndrome and glaucoma, was recently identified as a target for RXRα binding to regulate its transcription and expression." (PMID 35682657, 2022). "In addition, a summary of the roles of both LOX and LOX-PP in diabetic retinopathy, and brief mentions of the roles for LOX and closely related LOXL1 in glaucoma, and keratoconus, respectively, are included." (PMID 35563478, 2022). "Therefore, it is difficult to explain the pathophysiology of PEX syndrome and glaucoma with LOXL1 gene alone." (PMID 35418653, 2022). "LOXL1, encoding a cross-linking matrix enzyme, has been recognized as the major genetic effect locus for PEX syndrome and PEX glaucoma in all populations worldwide, although the biological role of the associated variants still remains unknown." (PMID 35682657, 2022). "Ultimately, modulation of LOXL1 gene expression could be promising and present a potential strategy for treatment of pesudoexfoliation and primary open angle glaucoma." (PMID 35563478, 2022). "Other genes involved in microfibril function, such as LOXL1 and LTBP2, are associated with human glaucoma, lending further support to our microfibril hypothesis of glaucoma." (PMID 30406200, 2018). "We confirmed the association between LOXL1 and XFS and XFG in a significant number of well-ascertained patients originating from Epirus, Greece (all examined by the same experienced ophthalmologist specializing in glaucoma, Prof. G. Kitsos)." (PMID 23687437, 2013). "Lysyl oxidase-like 1, which is linked to Pseudoexfoliation (PEX) glaucoma, and which is heavily bound to the PEX material of PEX patients was very downregulated in Q368X, while other two PEX relevant components, FBN1 and Fibulin 5 (FBLN5), were slightly altered in all four mutants." (PMID 22615763, 2012). "We have recently shown that the “G” allele frequencies of both rs1048661 and rs3825942 SNPs of the lysyl oxidase-like 1 (LOXL1) gene differed between pseudoexfoliation glaucoma (PEG) patients and control subjects from Saudi Arabia (p=0.0056 and p<0.0001, respectively)." (PMID 22065931, 2011). "The identification of lysyl oxidase-like 1 (LOXL1) as a major genetic risk factor for PEX syndrome and PEX glaucoma further supports a role of elastogenesis and elastosis in the pathophysiology of PEX, as LOXL1 is a pivotal cross-linking enzyme in elastic fiber formation and stabilization." (PMID 21572731, 2011). "We also investigated the effects of four glaucoma drug medications on LOXL1 expression in primary human lens epithelial cell cultures to see if they could affect LOXL1 expression." (PMID 21139690, 2010). "Our results also revealed that the LOXL1 gene is not a susceptibility gene of other types of glaucoma other than XFG." (PMID 20142848, 2010). "Three SNPs of LOXL1 (rs1048661, rs3825942, and rs2165241) were screened in a cohort of 78 unrelated and clinically well characterized glaucoma cases comprising of PG (n=44) and PDS (n=34) patients as well as 108 ethnically matched normal controls of Caucasian origin." (PMID 18618003, 2008). "Replication studies in the Swedish population confirmed genetic susceptibility of LOXL1 polymorphisms to exfoliation with (XFG) or without glaucoma (XFS)." (PMID 18385788, 2008). "The implicated LOXL1 polymorphisms have not been associated with primary open-angle glaucoma (POAG)." (PMID 19098994, 2008). "Most recently, one study from Japan reported a lack of association between LOXL1 polymorphisms and primary open-angle glaucoma in two of three SNPs (e.g., rs1048661 and rs3825942)." (PMID 18958304, 2008).
glaucoma (continued). "Previously, a lack of association between LOXL1 polymorphisms and primary open-angle glaucoma or primary angle-closure glaucoma were reported in Caucasian, African American, Ghanaian, and Indian populations." (PMID 18958304, 2008). "LOXL1 lacked any association with primary open-angle glaucoma or normal tension glaucoma in this population." (PMID 18958304, 2008). "Nevertheless, the effects of the identified LOXL1 risk variants in the presence of potentially co-modulating external factors, such as TGF-ß1 or oxidative stress, need to be characterized to better understand the functional relevance of LOXL1 in the pathophysiology of PEX syndrome/glaucoma." (PMID 21572731, 2011). "This hitherto unique observation argues against a causal role of rs3825942 in PEX pathophysiology and suggests that other as yet unknown causal variants of LOXL1, e.g. affecting its promoter or other regulatory regions, may contribute to the genetic risk of PEX syndrome/glaucoma." (PMID 21572731, 2011). "In addition, we compared the frequencies of LOXL1 polymorphisms by dividing the phenotypes of XFS into either XFS without glaucoma or XFG and into either unilateral or bilateral involvement." (PMID 22128228, 2011). "However, the LOXL1 genetic predisposition is only limited to exfoliation with or without glaucoma and does not include the POAG phenotype." (PMID 18385788, 2008). "While we could not conclude the causality of the lack of LOXL1 in either axial myopia or glaucoma, the correlation of axial elongation and reduced RGC function further supports the notion of Loxl1−/− mice as an excellent rodent model to understand the association between glaucoma and myopia." (PMID 41009782, 2025). "Several compounds that target ECM synthesis and degradation pathways, such as decorin, lysyl oxidase-like 1 (LOXL1), and matrix metalloproteinases (MMPs), have been investigated for their potential as anti-fibrotic therapeutics in glaucoma." (PMID 37391006, 2023). "Transcriptome analysis at the tissue or cell level is also needed to identify gene networks involving LOXL1 in the pathogenesis of XFS and glaucoma." (PMID 34440405, 2021). "We first evaluated the prevalence of non-synonymous SNPs in LOXL1 in PEG patients and glaucoma-free controls and compared the results in both groups." (PMID 21197115, 2010). "The mild nature of this glaucoma phenotype in Loxl1−/− mice is not surprising given the fact that the Loxl1−/− mice did not have elevated IOP at any age." (PMID 41009782, 2025). "The investigation of glaucoma-related cross-linking proteins, such as lysyl oxidase (LOX)/lysyl oxidase-like 1 (LOXL1), tissue trans-glutaminase (TG2), and advanced glycation end products, will allow corneal gene therapy to be further developed into a promising treatment of glaucoma." (PMID 35652098, 2022). "Although lysyl oxidase-like 1 (LOXL1) is known as the principal genetic risk factor for pseudoexfoliation (PEX) syndrome, a major cause of glaucoma and cardiovascular complications, no functional variants have been identified to date." (PMID 28534485, 2017). "In this study, we divided the XFS group by phenotype (XFS without glaucoma and XFG, unilateral and bilateral XFS) and compared the allelic associations of the three LOXL1 SNPs to the different XFS subgroups." (PMID 23441117, 2013). "The drug treatment incubation studies suggest that the change in LOXL1 expression observed in XFG is not attributable to glaucoma drug therapy." (PMID 21139690, 2010). "List of PCR primers for LOXL1 (lysyl oxidase-like 1) exon sequencing in South African black individuals with or without exfoliation glaucoma." (PMID 20431720, 2010). "Demographic and clinical features of control subjects and primary open angle glaucoma patients with or without TT/GG compound genotype of rs1048661 and rs3825942 in LOXL1." (PMID 18636115, 2008).